MEN1 (menin 1)
Diseases named in the same sentence as MEN1 in open-access papers (continued):
Sharing a sentence is not in itself a finding about the gene and the disease.
pituitary adenomas (continued). "Both individuals with MEN1 pathogenic variants were diagnosed with MEN 1-related features, one with primary hyperparathyroidism and a leiomyoma and the second with primary hyperparathyroidism, a leiomyoma, and a pituitary adenoma." (PMID 35668420, 2022). "Two miRNAs, miR-15a and miR-16-1, that had been previously shown as having a significantly reduced expression in human sporadic pituitary adenomas, were reported to be downregulated also in MEN1 pituitary tumors from Men1+/− mice, with respect to the healthy pituitary tissue." (PMID 34298972, 2021). "Whereas 20% of the pituitary adenomas in patients with MEN1 are classified as prolactinomas, this type of tumor has not been reported in patients with MEN4, possibly indicating differential effects of CDKN1B and MEN1 mutations on development of lactotropic tumors in the pituitary gland." (PMID 30990521, 2019). "The most common mutation-negative MEN1 phenotype is the combination of primary hyperparathyroidism and a pituitary adenoma." (PMID 30254610, 2018). "Three additional sporadic cases had an atypical MEN1 [pituitary adenomas (one TSH-secreting and 2 non-functioning) associated with adrenal tumors (one cortisol-secreting and 2 non-functioning)]." (PMID 29036195, 2017). "Our previous work documented vacuolated cytoplasm in SDH-mutated adenomas but not in patients with pituitary adenomas and phaeochromocytomas due to MEN1 or VHL genes." (PMID 28284009, 2017). "A history of primary hyperparathyroidism or pituitary adenoma in patients with GEP-NET is strongly suggestive of MEN1, and genetic testing should be carried out to allow for extended family testing; while a personal or family history of phaeochromocytoma/paraganglioma is suggestive of NF1 or VHL." (PMID 28965289, 2017). "Finally, the case we describe demonstrates the importance of a detailed family history and the role of genetic testing for MEN1 and AIP mutations in all cases of pediatric pituitary adenoma." (PMID 26180530, 2015). "However, the different Men1 mouse models also show slight phenotypic differences including the type of pituitary adenomas developed." (PMID 25136513, 2014). "Thus, conditional inactivation of the MEN1 gene using a mouse line in which Cre expression was driven by the insulin promoter resulted in the formation of pituitary adenomas (in addition to islet tumors) by 12 months of age." (PMID 25136513, 2014). "Thirty-one (29%) index cases presented the classical triad of MEN1-related tumors, 37 (35%), PHPT and GEP tumors, and 31 (29%) PHPT and pituitary adenomas." (PMID 37484956, 2023). "Familial MEN1 (n = 129): In the whole series, PHPT was present in 119 (92%) patients, GEP tumors in 90 (70%), pituitary adenoma in 45 (35%), and adrenal lesions in 43 (33%)." (PMID 37484956, 2023). "A large French series highlighted a shorter delay to achieve the diagnosis of MEN1 when the first manifestation of the syndrome is a NET, as compared to hyperparathyroidism or pituitary adenomas." (PMID 37761922, 2023). "Clinical guidelines focus on early detection of MEN1-related tumors, namely parathyroid adenomas, GEP NETs, and pituitary adenomas." (PMID 33312161, 2020). "Analysis of tumor tissue from the pituitary adenomas and the pheochromocytomas/paragangliomas demonstrated SDHB LOH in three pituitary adenomas and LOH of MEN1 in two pheochromocytomas." (PMID 30456751, 2018). "Tumor tissue analysis identified LOH at the SDHB locus in three pituitary adenomas and LOH at the MEN1 locus in two pheochromocytomas." (PMID 25494863, 2015). "At this time, the diagnosis of recurrent pituitary adenoma was confirmed, but it was unclear if the second tumor was de novo synchronous malignancy, or a MEN1-driven non-pituitary malignant neoplasm." (PMID 41155355, 2025).
pituitary adenomas (continued). "Prolactinomas also occur in the setting of familial isolated pituitary adenoma (FIPA) kindreds, in which two or more related members in a family have isolated pituitary adenomas in the absence of MEN1 or other multiple endocrine neoplasias." (PMID 37711900, 2023). "In MEN1 patients SSA are for duodeno-pancreatic NET and pituitary adenomas." (PMID 36998475, 2023). "A retrospective study of 80 children and adolescents with MEN1 included 18 patients with pituitary adenomas but none was found to have CD." (PMID 37409236, 2023). "Among the group of S-MEN1 patients who tested negative for MEN1 mutations (80%), 82% had two main MEN1-related lesions (70% of them had PHPT and pituitary adenoma, and 30% had PHPT and GEP), whereas the remaining 18% had the classical triad." (PMID 37484956, 2023). "Mean age of these patients at MEN1 diagnosis was 39.4 ± 11 years, and PHPT was the initial manifestation in the majority of them (77.2%, n = 17); in four patients the first diagnosis was a NET and in one patient a pituitary adenoma." (PMID 35407574, 2022). "Herein, one patient with AA presented with familial MEN1 syndrome characterized by AA and pituitary adenoma; the patient harbored two somatic CDC73 alterations (c.9_18delCGTGCTTAGC: p.Asp3Glufs∗15, c.571delG: p.Ala191Leufs∗11) but lacked MEN1 mutation." (PMID 33778063, 2021). "In MEN1 patients with acromegaly and enlarged pituitary gland with no discernable pituitary adenoma, a GHRH-secreting neuroendocrine tumor, typically arising from the pancreas should also be considered." (PMID 28161730, 2017). "Germline mutations of the Aryl-hydrocarbon Interacting Protein (AIP) gene, the gene responsible for some sporadic pituitary adenomas, and a subset (20%) of Familial Isolated Pituitary Adenoma (FIPA), have been detected in a few cases of sporadic PHPT and one MEN1 kindred." (PMID 29036195, 2017). "Due to the fact that primary hyperparathyroidism is present in the majority (approximately 90%) of MEN1 patients, parathyroid hyperplasia/adenoma/carcinoma should be ruled out in all cases of apparently sporadic pituitary adenomas." (PMID 26124750, 2015). "Familial isolated pituitary adenoma (FIPA) is a rare syndrome defined as familial presentation of pituitary adenomas in the absence of evidence for MEN1 and Carney complex." (PMID 25136513, 2014). "Three (8.6%) MEN1 patients had a history of hypercortisolism: 1 patient suffered from bilateral adrenal gland hyperplasia, 1 had ACTH-secreting neuroendocrine tumor in the pancreas and nodular cortical hyperplasia of the adrenal glands, and 1 had ACTH-secreting pituitary adenoma." (PMID 39575107, 2024). "Also, patients with three of the four criteria are frequently non-mutated for MEN1 or MEN4 syndrome, although the occurrence of pituitary adenoma or primary hyperparathyroidism increases the chance of a positive genetic test." (PMID 37761922, 2023). "The commonest clinical manifestations of MEN1 include parathyroid adenomas/hyperplasia resulting in primary hyperparathyroidism (in more than 90% of patients), NEN (more frequently within the pancreas, up to 70% of patients), and pituitary adenomas (in about 50% of cases)." (PMID 34681263, 2021). "Interestingly, all cases of PHPT or pituitary adenomas associated with adrenal tumors were MEN1-mutation negative whereas, respectively, 60% and 20% of PHPT or pituitary combined with carcinoids, were MEN1-mutation positive." (PMID 29036195, 2017). "In addition, we found LOH at the SDH locus in pituitary adenomas and at the MEN1 locus in pheochromocytomas, suggesting, although not proving, that in these patients a single gene is responsible for both tumors." (PMID 25494863, 2015). "Therefore, the pituitary adenomas and thyroid carcinoma exhibited by the present patient may be considered as early manifestations of MEN1 as opposed to pure endocrine tumors." (PMID 25663877, 2015).
pituitary adenomas (continued). "Heterozygous (Men1+/-) mice developed pituitary tumors, mostly reported somatolactotrophinomas and ACTH secreting pituitary adenomas but also nonfunctioning tumors." (PMID 25870702, 2014).
neuroendocrine tumors (83 papers, 2005 to 2026). "MEN1 is an autosomal dominant disorder caused by mutations in the MEN1 gene, leading to the development of various tumors including neuroendocrine tumors of the parathyroid, pituitary, and pancreas." (PMID 41008933, 2025). "Patients with MEN1 are at risk of developing neuroendocrine neoplasms (NEN) in the pancreas, duodenum, and pituitary." (PMID 40277511, 2025). "Carcinoid-like LCNEC shares multiple endocrine neoplasia 1 (MEN1) mutations with neuroendocrine tumor (NETs)." (PMID 40144596, 2025). "Neuroendocrine neoplasms (NEN) are associated with an increased risk for mortality in patients with MEN1." (PMID 39826015, 2025). "Deleting Men1 in Gfap+ cells causes these cells to promote neuroendocrine tumors in the gut and pancreas, which suggests a glial or neural crest cell origin for these tumors." (PMID 39546562, 2025). "Malignant neuroendocrine tumors caused by MEN1 gene mutations are associated with worse prognosis and are the most common cause of death in patients with MEN1." (PMID 38730578, 2024). "MEN1 gene that is traditionally known for its germline mutations in neuroendocrine tumors is associated with high risk of developing breast cancer in females with MEN1 syndrome." (PMID 37437063, 2023). "Neuroendocrine tumors are linked to several genetic syndromes, including Multiple endocrine neoplasia type 1 (MEN1), type 4 (MEN4), and von Hippel–Lindau syndrome." (PMID 37239385, 2023). "Multiple Endocrine Neoplasia 1 (MEN1) syndrome is a genetic condition arising from a mutation of the MEN1 gene resulting in neuroendocrine tumor formation." (PMID 35919366, 2022). "Such patients are at high risk for the development of a variety of neuroendocrine neoplasms, including pancreatic neuroendocrine carcinomas, which are often not amenable for curative surgical resection and account for the mortality of MEN1 patients." (PMID 39034953, 2022). "Comparison of the histological features of islet lesions between Men1–/– and hTS/Men1–/– mice for each age group showed that hTS overexpression was associated with accelerated neuroendocrine tumor development in comparison with Men1–/– controls." (PMID 36048542, 2022). "Among syndromic manifestations, pathogenic MEN1 variants that cause MEN1 syndrome account for the most well-defined inherited syndrome that can feature thoracic neuroendocrine tumors." (PMID 33641055, 2021). "MEN1 gene mutations have evolved from inherited tumor syndromes to recognizing the role of somatic MEN1 mutations in sporadic neuroendocrine tumors." (PMID 33716975, 2021). "Overall, MEN1 is the most frequently somatically mutated gene in neuroendocrine tumors (identified in 11–22% of carcinoids), which is usually associated to loss of heterozygosity." (PMID 33641055, 2021). "Despite advances in the diagnosis and treatment of MEN1-associated tumors, patients with MEN1 continue to have decreased life expectancy primarily due to malignant neuroendocrine tumors." (PMID 31263451, 2019). "Conversely, a delay in MEN1 diagnosis has been found to cause advanced metastatic neuroendocrine tumor manifestations." (PMID 31727021, 2019). "The two-hit pathogenic mechanism of MEN1 was revealed by two different somatic mutations in the parathyroid carcinoma tissue of II-3 and a novel somatic mutation in the thoracic neuroendocrine tumor tissue of III-6." (PMID 29416715, 2018). "In a different study, MEN1 and DAXX were shown to repress the expression of the membrane metalloendopeptidase (MME) and mutations in MEN1 or DAXX result in loss of this repression leading to neuroendocrine tumor proliferation." (PMID 30315258, 2018). "Sporadic pancreatic endocrine/neuroendocrine tumors of the hormone secreting islet cells of the pancreas harbor inactivating mutations in MEN1 encoding menin, a component of histone methyltransferase complexes, in 27–44% of tumors." (PMID 22666422, 2012).
neuroendocrine tumors (continued). "However, functional imaging, particularly 68Ga-DOTATATE PET/CT, has emerged as a highly effective approach for detecting neuroendocrine tumors associated with MEN1 and providing crucial data for long-term surveillance." (PMID 40144450, 2025). "Intriguingly, inactivating mutations in MEN1 can drive neuroendocrine tumour development." (PMID 36635503, 2023). "Patients with MEN1 are at a higher risk of developing Zollinger-Ellison syndrome (ZES) due to the growth of neuroendocrine tumors called gastrinomas that release gastrin leading to hypersecretion of acid in the stomach resulting in severe ulcerative disease of the upper GI tract." (PMID 35919366, 2022). "Similarly, ARMC5 (OMIM: 615549; 16p11.2) variants have also been found to cause sporadic neuroendocrine tumors and multiple endocrine neoplasia type-1 (MEN1; OMIM: 131100)." (PMID 36553564, 2022). "The advancement of neuroendocrine tumors is the leading cause of death among MEN1 patients." (PMID 32884006, 2020). "It is impossible to exclude that clinically diagnosed mutation-negative MEN1 patients, might harbor a yet unknown mutation to either the MEN1 gene or any other gene that predisposes for neuroendocrine tumor development." (PMID 30254610, 2018). "This is the first analysis of global gene expression in MEN1-associated neuroendocrine tumors." (PMID 15691381, 2005). "Beyond these 3 major manifestations, individuals with MEN1 also develop neuroendocrine tumors of the lung, thymus, gastrointestinal tract, and adrenal cortex." (PMID 40581735, 2026). "MEN1-gastrinomas are aggressive neuroendocrine tumors (NETs) that arise predominantly in the submucosal Brunner's glands of the duodenum, an organelle rich in extracellular growth factors." (PMID 41993411, 2026). "The algorithm's original training dataset comprised patients with sporadic PanNETs and did not specifically account for the simultaneous occurrence of diverse neuroendocrine neoplasms, as is characteristic in MEN1." (PMID 40581735, 2026). "Neuroendocrine tumors also known as carcinoid tumors, most commonly occur sporadically but may be associated with hereditary syndromes such as multiple endocrine neoplasia type 1 (MEN1), neurofibromatosis type 1 (NF1), von Hippel–Lindau disease (VHL), and, more rarely, tuberous sclerosis." (PMID 40869648, 2025). "The protein encoded by the murine Men1 gene has a close similarity of 97% to the human tumor suppressor protein MENIN, and heterozygous Men1(+/T) knockout mice develop various neuroendocrine neoplasms mimicking the MEN1 syndrome in humans." (PMID 40277511, 2025). "MEN1 diagnosis was subsequently suspected due to widespread neurofibromas, paternal history suggestive of neuroendocrine tumors and the patient’s origin from a region with high disease prevalence." (PMID 40476723, 2025). "Gastrinomas, which cause Zollinger–Ellison syndrome (ZES), are the most common functional duodenopancreatic neuroendocrine tumors (NETs) in MEN1, affecting 21–70% of patients." (PMID 39201946, 2024). "Infrequently, neuroendocrine neoplasms (NENs) connected to MEN1 are diagnosed in diverse anatomical sites, including the stomach, thymus, lung, bronchopulmonary tract (in 3–10% of cases), and, more recently, in the female breast (about 7%)." (PMID 39201946, 2024). "Genetic testing of MEN1 gene and screening of other neuroendocrine tumors were performed for this patient, due to the development of multiple parathyroid adenomas." (PMID 37795364, 2023). "In MEN1, parathyroid tumors are the most frequent neuroendocrine tumors, observed in over 85% of patients, leading to primary hyperparathyroidism." (PMID 37239385, 2023).
neuroendocrine tumors (continued). "In MEN1, it is indeed recommended to investigate the presence of neuroendocrine tumors even in asymptomatic subjects, performing periodic biochemical and imaging investigations." (PMID 35355569, 2022). "MEN1 is a complex, rare, syndrome inherited in an autosomal dominant tract and characterized by the development of multiple neuroendocrine tumors, requiring lifelong surveillance and multiple medical and surgical therapies throughout the patient’s life." (PMID 33407684, 2021). "The identification of specific expression profiles of miRNAs specifically characterizing neuroendocrine tumor cells in MEN1 patients is an important step for the future development of target RNA antagomirs-based strategies to control the MEN1 tumorigenesis." (PMID 33066578, 2020). "MEN1-related neuroendocrine tumors often show hematogenous metastasis, with the liver being the most common metastatic site." (PMID 31727021, 2019). "A 43-year-old male with a history of MEN1 and multiple subcentimeter neuroendocrine tumors with elevation of PP was treated with octreotide therapy leading to a reduction and normalization of PP levels." (PMID 31183223, 2019). "Our review of known MEN4 cases indicates that the prevalence of gastroenteropancreatic neuroendocrine tumors is lower in patients with MEN4 than in MEN1, in which 30% to 70% develop enteropancreatic tumors, and 10% develop gastric tumors." (PMID 30990521, 2019). "Pancreatic lesions suggesting MEN1-related neuroendocrine tumours were identified on endoscopic US, while CT scan detected a non-functional adrenal nodule." (PMID 31142320, 2019). "Non-endocrine multiple skin lesions are also frequent (i.e collagenomas, angiofybromas, fibromas, angiomas, and lipomas), often manifesting even before of MEN1 neuroendocrine tumours and being, thus, useful in favoring an early diagnosis." (PMID 30428914, 2018). "At the time of the subsequent MEN1 diagnosis in the family members of the index cases, 30 (12.1%) had a duodenopancreatic neuroendocrine tumor, of whom 20% already had metastatic disease." (PMID 30254610, 2018). "An uniglandular pHPT therefore seems to increase the likelihood of co-incidence of two sporadic neuroendocrine tumors instead of true MEN1." (PMID 30254610, 2018). "The second most common manifestation in MEN1 are neuroendocrine tumours of the GEP tract (GEP-NETs), affecting about 30–70% of patients, usually manifesting as multiple adenomas and often recurrent after surgical resection." (PMID 30428914, 2018). "Functioning entero-pancreatic MEN1-neuroendocrine tumors characterized by hormonal hypersecretion syndromes should be operated upon at the moment of diagnosis." (PMID 24213321, 2012). "Although no prospective randomized trial has been conducted on the validity of EUS in monitoring MEN1-neuroendocrine tumors, this imaging study seems to be the most accurate in baseline diagnosis or during the follow-up of patients." (PMID 24213321, 2012). "The natural history of MEN1-neuroendocrine tumors is not completely known, since few patients have been studied prospectively with a protocol based on high sensitivity diagnostic tools." (PMID 24213321, 2012). "Preoperative US, MRI, or CT rarely localize lesions less than 1 cm, therefore missing most smaller MEN1-neuroendocrine tumors." (PMID 24213321, 2012). "Global gene expression studies on eight neuroendocrine tumors from MEN1 patients and 4 normal islet controls was performed utilizing Affymetrix U95Av2 chips." (PMID 15691381, 2005). "This first study of global gene expression in neuroendocrine tumors arising in the pancreas of patients with the MEN1 syndrome has identified many genes that are differentially expressed, as compared with normal human islet cells." (PMID 15691381, 2005).